ERBB2 (erb-b2 receptor tyrosine kinase 2)
Diseases named in the same sentence as ERBB2 in open-access papers (continued):
Sharing a sentence is not in itself a finding about the gene and the disease.
dilated cardiomyopathy (continued). "Mice with a cardiac-specific deletion of ErbB2 develop dilated cardiomyopathy and demonstrate a robust systolic dysfunction after pressure overload compared with wild-type mice, which confirms that the ErbB2 pathway is cardioprotective." (PMID 29743983, 2018). "ERBB2 is essential in the prevention of dilated cardiomyopathy, which is required for maintenance of cardiac contractility." (PMID 26101539, 2015). "In the postnatal heart, ErbB2 conditional knockout mice develop dilated cardiomyopathy at eight weeks of life." (PMID 24826288, 2013). "Moreover, the lack of cardiac trabeculae is observed in ErbB2 (ortholog of HER2)-knockout mice, and the features of dilated cardiomyopathy are observed in ventricular-specific ErbB2-knockout mice." (PMID 39125956, 2024). "Indeed, mice with ventricular-restricted deletion of ERBB2 exhibited multiple independent parameters of dilated cardiomyopathy, such as chamber dilatation, wall thinning, and decreased contractility." (PMID 35497981, 2022). "In addition to the known missense variant (rs2234962) in the BAG3 locus for dilated cardiomyopathy, we identify deleterious or damaging protein-coding variants in genes SYNPO2L, ERBB2, and STARD3 in strong LD with sentinel SNPs (LD R2 > 0.8)." (PMID 36517512, 2022). "When an experiment was conducted to better understand the effect of ErbB2 in adult heart mutant mice with a cardiac-restricted removal of ErbB2, these ErbB2 mutants showed a number of signs of dilated cardiomyopathy, including chamber dilation, wall thinning, and decreased contractility." (PMID 34681194, 2021). "However, subsequent studies have discovered that ERBB2 plays an important role in maintaining cardiomyocyte health, evidenced by the spontaneous dilated cardiomyopathy that results from ERBB2 knockout." (PMID 28951721, 2017). "Thus, increasing expression or activation of ErbB2 might prevent dilated cardiomyopathy and heart failure accordingly." (PMID 34408653, 2021). "Similarly, the deletion of Erbb2 in adult cardiomyocytes causes early cardiac dysfunction and severe dilated cardiomyopathy in the absence of readily demonstrable cardiomyocyte apoptosis." (PMID 25269082, 2014). "Indeed, numerous studies have shown that ErbB2 and ErbB4 receptor signaling are essential for maintenance of myocardial function in the adult heart because CM specific deletion of functional receptors produces dilated cardiomyopathy." (PMID 25206341, 2014). "Interestingly, prior work showing the inhibition of ErbB2, a member of the EGF receptor family, in transgenic knock-out mice or individuals that received herceptin chemotherapy is associated with the development of dilated cardiomyopathy." (PMID 20523889, 2010). "For example, decreased MYL2 and MYH6 gene expression coincided with increased RYR2, HCN4, CORIN, NPPA, ERBB2, and MYH7 gene expression in hypertrophic and/or dilated cardiomyopathy." (PMID 32804947, 2020). "It has been reported that cardiac-specific mutant of ErbB2, a member of the EGFR/erbB family, shows a severe dilated cardiomyopathy in mice." (PMID 22216087, 2011). "Because disruption of NRG1/ErbB signaling leads to dilated cardiomyopathy, an imbalance in the EC (NRG1)-CM (ErbB2/4) signaling may contribute to DCM." (PMID 25206341, 2014).
acute myeloid leukemia (31 papers, 2014 to 2025). Acute myeloid leukemia (AML) is a group of neoplasms arising from precursor cells committed to the myeloid cell-line differentiation. "Mubritinib was initially described as an ERBB2 inhibitor but was recently found to inhibit OXPHOS in acute myeloid leukaemia (AML) models." (PMID 39901019, 2025).
Hodgkins lymphoma (31 papers, 2012 to 2025). A heterogeneous group of malignant lymphoid neoplasms of B-cell origin characterized histologically by the presence of Hodgkin and Reed-Sternberg (HRS) cells in the vast majority of cases. "The recent approval of SGN-35 (Adcetris), an anti-CD30 Auristatin ADC for the treatment of Hodgkin's lymphoma and Trastuzumab Emtansine (T-DM1), an anti-Her2/ErbB2 ADC for the treatment of malignant breast cancer, provides evidence of these improvements." (PMID 24454709, 2014).
interstitial lung disease (31 papers, 2020 to 2026). A diverse group of lung diseases that affect the lung parenchyma. "After three cycles of ERBB2-targeted antibody-drug conjugate combined with programmed death-1 (PD-1) inhibitor, transient Grade 1 interstitial lung disease resolved with steroids." (PMID 40494858, 2025).
prostate tumors (31 papers, 2003 to 2026). "The analysis presented here implicates over-expression of Myc, Akt, c-Src, or erbB-2/HER2 with activation of their associated pathways in at least a subset of prostate tumors." (PMID 18350153, 2008). "Studies have found high levels of expression of ITGB4 in prostate cancer, where ITGB4 in prostate tumor progenitor cells amplifies ErbB2 and Met signaling transduction." (PMID 39239559, 2024). "In several Oncomine datasets, EGFR and/or ERBB2 mRNA levels also increased in prostate tumors compared to normal tissues." (PMID 31792211, 2019). "In addition, some studies have also highlighted a role of PGC-1α either in the enhancement of fatty acid oxidation observed in breast and prostate tumors, or in the activation of lipogenesis in colon cancer and in ERBB2/Neu-induced breast cancer." (PMID 29865240, 2018). "Through the regulation of ErbB2 and c-Met signals, ITGB4 promotes the self-renewal and transportation amplification of prostate tumor progenitor cells, as well as rapid proliferation of tumor cells." (PMID 39239559, 2024). "Analyses of human prostate tumor specimens suggest that PI3K/AKT and MEK/ERK signaling pathways are frequently activated by IGF-1, ErbB2, and VEGF in prostate tumors, via the phosphorylation, subsequent activation of NF-κB, Bcl2 protein, and deactivation of p21 and Bad protein." (PMID 25003983, 2014). "Moreover, recombinant humanized ERBB2 monoclonal antibody pertuzumab prevents dimerization of ERBB2 with EGFR and ERBB3 to prevent activation of downstream pathways, which is demonstrated to be inhibiting breast and prostate tumor growth." (PMID 38216592, 2024). "However, up to now, there is no conclusive evidence that links ERBB2 or RAS activation to the invasive cell behavior in prostate tumors." (PMID 24937171, 2014). "Studies indicate that MIEN1 overexpression is linked to genomic amplification of the ERBB2 locus, since its sufficient expression is noted in the ERBB2 nonamplified breast and prostate tumors, suggesting that MIEN1 might have an independent functional promoter." (PMID 31552186, 2019).
carcinosarcoma (29 papers, 2010 to 2025). A malignant tumor composed of a mixture of carcinomatous and sarcomatous elements. "Given the precedence in targeting ERBB2-amplified/HER2-expressing carcinosarcoma, we focused our attention on FGFR1 copy number gain/amplification as another potentially targetable alteration in carcinosarcoma." (PMID 41202566, 2025). "Among the more aggressive EC subtypes, 86% of the grade 3 endometrioid tumors, 95% of serous lesions, 88% of carcinosarcomas, 89% of clear cell, and 77% of undifferentiated were ERBB2-positive (≥1+)." (PMID 39235791, 2024). "Assessment of Trim24COE carcinosarcoma tumors by IHC revealed gain of vimentin, loss of E-cadherin, estrogen receptor (ER) and progesterone receptor (PR), and no over-expression of receptor tyrosine kinase erbB-2 (ERBB2)." (PMID 34508101, 2021).
renal carcinoma (28 papers, 2005 to 2025). A carcinoma arising from the epithelium of the renal parenchyma or the renal pelvis. "Regarding lung metastases, CAR-NK-92 cells targeting ERbB2/HER2 have shown to reduce tumor growth in an experimental mouse model of lung metastases from renal carcinoma." (PMID 40519903, 2025). "COMMD5/HCaRG overexpression inhibited tumor growth and angiogenesis in a homograft renal carcinoma mouse model by promoting de-phosphorylation of ErbB2/HER2, ErbB3/HER3, and EGFR, leading to inhibition of ErbB signaling pathways." (PMID 33768002, 2021). "The ability of the liposomal vaccines to induce ErbB2-specific CTL responses and their antitumoral effects were investigated in immunocompetent BALB/c mice, using ErbB2-expressing murine renal carcinoma cells as a model." (PMID 15812545, 2005). "Specific cytolysis of target cells via the ErbB2-CAR was demonstrated using mouse renal carcinoma (Renca) cells with our without human ErbB2 expression, which do not express human MHC or NKG2D ligands." (PMID 29029499, 2017). "We next investigated if the ability of the dI (F4) or dIII (A5) specific IgGs to block signaling correlated with the ability to inhibit growth of a panel of ERBB2-positive breast (BT-474 & SK-BR-3) and gastric (NCI-N87) cells as well as the EGFR-positive renal cancer cell line (ACHN)." (PMID 25386657, 2014). "In a murine model system, vaccination with these constructs completely protected BALB/c mice from subsequent s.c. challenge with ErbB2-expressing, but not ErbB2-negative, murine renal carcinoma (Renca) cells, indicating the induction of potent, antigen-specific immune responses." (PMID 15812545, 2005).
serous ovarian cancer (27 papers, 2012 to 2025). "Using a whole‐genome mate‐pair next generation sequencing (MPseq) protocol, we identified several high grade serous ovarian cancers (HGS‐OC) with DNA alterations in genes encoding members of the ERBB2 pathway." (PMID 30499260, 2019). "We additionally tested the drugs ex vivo using a highly invasive ErbB2-positive high-grade human serous ovarian cancer cell line OVC316 that expresses full-length ErbB2." (PMID 33939112, 2021). "We report the case of a young woman with a FIGO stage IV high-grade serous ovarian cancer with an amplification of ERBB2." (PMID 34095423, 2021). "From genetic perspectives, the low grade serous ovarian carcinoma is characterized by mutations in KRAS, BRAF or ERBB2 genes; whereby approximately 66% of cases have mutations in at least one of these genes with the ERBB2 being the least frequently mutated." (PMID 25404506, 2014).
skin cancer (27 papers, 2014 to 2025). "The ERBB2 S310F mutation found in Case 2 is well known from cancers of the skin, urinary tract, and cervix." (PMID 40665654, 2025). "GSEA analysis showed that samples with FAT3 mutation enriched in “ERBB2 Breast Preneoplastic UP”, “Kras Oncogenic Signature”, “Malignant Skin Tumor DN”, “MCV6 LCP With H3K27ME3”, and “MET Signaling”." (PMID 33816234, 2021). "The results of GSEA analysis showed that samples with FAT3 mutation enriched in “ERBB2 Breast Preneoplastic UP”, “Kras Oncogenic Signature”, “Malignant Skin Tumor DN”, “MCV6 LCP With H3K27ME3”, and “MET Signaling”." (PMID 33816234, 2021). "Transgenic mice expressing rat ErbB-2 under the bovine keratin 5 promoter, which was aimed at developing skin tumors, also developed GBC, underscoring the oncogenic potential of ErbB-2." (PMID 34064809, 2021). "Human skin cancer A431 cells, which are widely used in ErbB1 research, overexpress ErbB1 and also express a low level of ErbB2." (PMID 27286447, 2016). "In addition, ERBB2, a member of the EGFR family, is expressed in the epidermis and hair follicle root sheath, and overexpression of ERBB2 has also been found in skin cancer patients." (PMID 36530656, 2022). "ERBB4 is a well-known oncogene in skin cancer and found to be mutually exclusive with ERBB2." (PMID 34899838, 2021). "Other proteins (AKT, ERBB2, HRAS, and CCND1) are also reported to have a part in skin cancer." (PMID 34466445, 2018). "For instance, a study on Pongamia pinnata extract against skin cancer demonstrated that MD simulations were essential in verifying the stability of the complexes EGF-Pazopanib, EGFR-Pongachromene, and ERBB2-Vitexin up to 100 ns without any major fluctuation." (PMID 40627263, 2025).
papillary thyroid cancer (26 papers, 2006 to 2025). "Similarly, the translational regulation of pancreatic and duodenal homeobox 1 (PDX1) in pancreatic β cells and ERBB2 in radioiodine-refractory papillary thyroid cancer also relies on IGF2BP2’s recognition of m6A methylation." (PMID 39596216, 2024). "For example, in papillary thyroid cancer, IGF2BP2 increases the translational efficiency of erb-b2 receptor tyrosine kinase 2 (ERBB2) by binding to m6A motifs in its coding sequence (CDS), thereby conferring resistance to tyrosine kinase inhibitors." (PMID 39596216, 2024). "Epidermal growth factor receptor 2 (ERBB2) is commonly over-expressed in advanced or metastatic tissues of papillary thyroid cancer (PTC) with poor prognosis, while it remains unknown whether ERBB2 plays a role in the progression of PTC." (PMID 36437939, 2022). "Papillary thyroid cancer model TPC-1 did not express p-EGFR under any of the tested conditions (data not shown), whereas ErbB2 protein was always expressed and particularly increased after PD and EGF alone treatments." (PMID 35269445, 2022).
pneumonitis (26 papers, 2020 to 2026). An inflammatory process affecting the lung parenchyma. "Despite the high anti-tumor activity of T-DXd, optimizing the management of ILD/pneumonitis is critical for its application in ERBB2-mutated NSCLC." (PMID 41154672, 2025). "ILD/pneumonitis was reported in a subset of patients, including grade ≥3 events, but no ILD-related fatal events were reported among patients with non-TKD ERBB2 mutations." (PMID 41835718, 2026).
oral cancer (25 papers, 2003 to 2026). "There is only one systematic review and meta-analysis related to the prognostic implications of EGFR2 (ErbB2) overexpression in oral cancer, which reports its association with decreased survival and increased metastatic involvement of the neck lymph nodes." (PMID 37569265, 2023). "Previous research by our group showed that E6/E7 of HPV type 16 along with ErbB-2, which is upregulated in 30% of oral carcinomas, induce cellular transformation of oral epithelial cells via β-catenin tyrosine phosphorylation by pp60 (c-Src) kinase activation." (PMID 32774155, 2020). "The ErbB2 levels in oral cancer have been proposed as a molecular marker for disease prognosis." (PMID 36359405, 2022). "In a murine model, ERBB2 expression was increased in alcohol-exposed mucosa, dysplasia, and invasive oral carcinomas, which may support our results." (PMID 24278325, 2013).
rhabdomyosarcoma (25 papers, 2011 to 2025). A rare aggressive malignant mesenchymal neoplasm arising from skeletal muscle. "Intriguingly, she emphasized that CIK-FFM cells can be engineered in-vitro with a second-generation CAR targeting, for example, the tumor-associated surface antigen ErbB2 (HER2/neu), a therapeutically useful target found in rhabdomyosarcoma (RMS) and other solid tumor entities." (PMID 38279995, 2024). "Here, we characterize and compare efficacy, phenotypic subpopulations and modes of action of CAR-CIK cells and conventional CAR-T cells from same-donor samples in ErbB2+ rhabdomyosarcoma (RMS)." (PMID 39963129, 2025). "Using FACS analysis, we noted that ErbB2 was expressed at low levels on all tested STS cell lines and on an established primary rhabdomyosarcoma cell line." (PMID 29029499, 2017).
apocrine carcinoma (24 papers, 2010 to 2025). "The main genetic lesion associated with molecular apocrine carcinoma in the literature is ERBB2 amplification." (PMID 20712882, 2010).
colorectal tumors (23 papers, 2011 to 2026). "The clinical relevance of ERBB2 mutants with higher risks of subsequent colorectal neoplasms suggests their prospects as molecular markers for high-risk SP identification." (PMID 35402217, 2022). "The ERBB2 mutation rate (15 %) in their series fulfilling Bethesda or Amsterdam II criteria was comparable to our LS colorectal tumors with 5/29 (17 %) showing high-frequency mutations." (PMID 29296220, 2017). "Thus, patients with ERBB2-mutated colorectal tumors may also benefit from these treatments." (PMID 41413856, 2025). "Our results are emphasizing that SP individuals with ERBB2 mutants are at higher risks of subsequent colorectal neoplasms." (PMID 35402217, 2022). "In addition, we observed ERBB2 amplification in CTCs, which has been described in colorectal tumors." (PMID 28978093, 2017). "Sera from 72 colorectal tumor patients (67 malignant and 5 benign tumors) were compared with 73 healthy donor sera for the presence of antibodies to CEA, EGFR, ErbB2 and ribosomal P proteins by western blotting or ELISA." (PMID 25889931, 2015).
congestive heart failure (23 papers, 2008 to 2025). Failure of the heart to pump a sufficient amount of blood to meet the needs of the body tissues, resulting in tissue congestion and edema. "The dual role of ErbB2 (or HER-2) in tumor growth and in physiological adaptive reactions of the heart positions ErbB2 at the intersection between cancer and chronic heart failure." (PMID 27596216, 2016).
cutaneous melanoma (23 papers, 2013 to 2025). A primary melanoma arising from atypical melanocytes in the skin. "ERBB2/3 is associated with myeloid-derived suppressor cells (MDSC) in cutaneous melanoma." (PMID 33732282, 2021). "Talantov’s dataset revealed another mRNA expression ERBB1 with a fold change of −7.657; that is, ERBB2 has a fold change of −3.952 and −2.229 in cutaneous melanoma compared with normal skin tissues in Riker’s and Talantov’s datasets, respectively." (PMID 33732282, 2021). "ERBB2/3 were related to MDSC in cutaneous melanoma, including human mononuclear myeloid-derived suppressor cells (M-MDSC) and polymorphonuclear myeloid-derived suppressor cells (PMN-MDSC), and may influence the progression of cutaneous melanoma through MDSC, but the conclusion needs further probing." (PMID 33732282, 2021). "In our study, it was found that ERBB2 is the low expression in cutaneous melanoma tissues, but this expression may not affect tumor stage and disease-free survival; however, it is related to the 5 years survival rates of cutaneous melanoma patients." (PMID 33732282, 2021). "Low expression of ERBB1/2 and high expression of ERBB3 were detrimental to the 5 years survival of cutaneous melanoma patients (ERBB1: log-rank P: 0.03; ERBB2: log-rank P: 0.008; ERBB3: log-rank P: 0.039)." (PMID 33732282, 2021). "The four ERBB tyrosine kinase family members [ERBB1 (epidermal growth factor receptor, EGFR), ERBB2 (HER2), ERBB3 (HER3), and ERBB4 (HER4)] (ERBB receptor family) have been shown, according to previous studies, to be related to the cutaneous melanoma." (PMID 33732282, 2021). "In the immunohistochemistry supplied by the HPA data set, we discovered that ERBB1 was moderately expressed, ERBB2 was lowly expressed, and the ERBB3/4 proteins were highly expressed in cutaneous melanoma." (PMID 33732282, 2021). "Besides, ERBB2/3 are closely related to MDSC, but the role of ERBB2/3 in the cutaneous melanoma population with MDSC remains to be further studied." (PMID 33732282, 2021). "In this study, we found that ERBB2/3 may be closely related to MDSC (Human M-MDSC and Human PMN-MDSC) in cutaneous melanoma." (PMID 33732282, 2021).